ARG1 (arginase 1)
Diseases named in the same sentence as ARG1 in open-access papers (continued):
Sharing a sentence is not in itself a finding about the gene and the disease.
tumor (continued). "MDSCs mainly inhibit T cell function by producing arginase I (Arg1), reactive oxygen species (ROS), and immunosuppressive cytokines such as IL-10 and TGFβ through activating STAT3, C/EBPβ, PI3K, and MAPK signaling pathways, which skews MDSCs into M2-like tumor-promoting phenotype." (PMID 35785030, 2022). "For this purpose, arginase-1 expression was analyzed in more than 14,000 tumor tissue samples from 117 different tumor types and subtypes as well as 76 non-neoplastic tissue categories by immunohistochemistry (IHC) in a tissue microarray (TMA) format in this study." (PMID 34943588, 2021). "M2 TAMs produce arginase 1 (ARG1), IL-10, transforming growth factor-beta (TGF-β), vascular endothelial growth factor (VEGF), matrix metallopeptidase 9 (MMP9) and prostaglandin E2 (PGE2), thus subverting anti-tumor adaptive immunity and promoting tumor development and spreading." (PMID 34572009, 2021). "Notably, Arg-1 and iNOS expression in the intestine was significantly diminished in STAT1-/- mice but not in WT mice during anti-IL-17 administration, which is consistent with the inhibition of tumor growth." (PMID 34299314, 2021). "However, the expression of several anti-inflammatory cytokines, such as CCL17, CCL22, IL-10, and TGF-β, and the M2 marker ARG1, was not significantly changed; these results were consistent with the transcriptome data in H22 tumor-bearing mouse liver tissue." (PMID 33710817, 2021). "Activated similar to M2 macrophages, TAMs express substantial amounts of ARG1, leading to an over-production of ornithine, which can be used by ODC to synthesize polyamines, such as putrescine, spermidine, and spermine, and thus promote cancer cell proliferation and tumor vascularization." (PMID 34037806, 2021). "The anti-tumor “N1” phenotype exhibited increased tumor cytotoxicity, elevated expression of CXCL13, CCL3, CCL6, CXCL10, TNFα and ICAM-1 and low ARG1 content, while the pro-tumor “N2” neutrophils expressed high levels of ARG1, MMP9, VEGF and several cytokines, including CCL2, CCL5, CCL17 and CXCL4." (PMID 34572138, 2021). "In the tumor ROI, we focused on stromal and epithelial tumor compartments and assessed their infiltration by monocytic CD11b+CD14+, granulocytic CD11b+CD15+, and immunosuppressive ARG1+ myeloid cells and also CD8+Ki67+/– cytotoxic and FOXP3+ regulatory T cells." (PMID 33193316, 2020). "Pairwise analysis showed significantly downregulated expression of ARG1 (by 2.2-fold, p = 0.025), DDAH1 (by 1.4-fold, p = 0.016), and DDAH2 (by 1.6-fold, p = 0.005) and upregulated expression of NOS2 (by 2.6-fold, p = 0.003) in tumor as compared to adjacent, macroscopically normal tissue." (PMID 32932854, 2020). "M2 macrophages, referred to as TAMs from hereon, inhibit anti-tumor immune responses through multiple mechanisms, most notably, through depletion of amino acids and production of immunosuppressive metabolites, such as indolamine-2,3-dioxygenase (IDO) and arginase 1 (ARG1)." (PMID 32731503, 2020). "Regarding the myeloid compartment, increased IL-6 signaling could aid to enhance the expression of immunosuppressive arginase-1 or to diminish major histocompatibility complex II (MHCII) and CD80 expression in dendritic cells (DCs), thereby supporting tumor immune escape mechanisms." (PMID 32604862, 2020). "Ridder and colleagues have shown that MDSCs are the major recombined cells in the tumor microenvironment after the uptake of exosomes and their RNA content and that MDSCs recombined with exosomal RNA display enhanced ARG1, TGF-β, and PD-L1 expression as compared to the non-recombined counterparts." (PMID 32793192, 2020). "Increased production of ROS, inducible nitric oxide synthase (iNOS), or arginase 1 (ARG1) released by neutrophils suppress CD8+ T lymphocyte antitumor activities and can reduce NK cell function, thereby facilitating the extravasation of tumor cells and promoting tumor growth and metastasis." (PMID 32354198, 2020).
tumor (continued). "The observation that the treatment produced an increase in the expression levels of ARG1 and MSR1 in NR, while a decrease in R patients supported the hypothesis that an alternative polarisation of macrophages occurred, improves tumour tolerance and generates anti-PD1 resistance." (PMID 32317723, 2020). "Clinical and experimental data indicate that, in the large majority of cancers, TAMs acquire an M2-like tumor-promoting phenotype characterized by high levels of immunosuppressive markers (e.g., ARG1, MMR1, IL10), as opposed to low levels of inflammatory cytokines (e.g., IL-12, IL1β, TNFα)." (PMID 32823961, 2020). "Thus, the conversion from arginine to urea and ornithine in the urea cycle because of increased intracellular Arg-1 in both TAMs and MDSC-LCs with tumor growth may exhibit effects on various metabolic pathways." (PMID 32518979, 2020). "PEGylated ARG1 (60 mg/kg) suppressed tumor growth in SK-MES-1 and SW900 but not H520 xenografts." (PMID 30808864, 2019). "Again, non-specific subtraction of the substrate for ARG1 may indirectly affect the host response to the tumor via effects on IDO1." (PMID 31354721, 2019). "Although ARG1 and iNOS are competitively regulated by Th1 and Th2 cytokines and complex intracellular biochemical pathways, including negative feed-back loops and competition for the same substrate, simultaneous activation of ARG and NOS pathways occurs in myeloid cells licensed by the tumor." (PMID 31333642, 2019). "Additionally, T lymphocyte proliferation is inhibited by high levels of Nitric Oxide (NO), and arginase 1 (Arg1) a potent metabolic enzyme induced and produced by an increase on MDSC population, this way several mechanisms of evasion of anti-tumor immune response by tumor cells are generated." (PMID 31662752, 2019). "The immune-suppressive environment in the ovarian tumor, rich in TGF-β, IL-10, VEGF, ARG-1, along with inhibitory molecules such as IDO, PD-1, and PD-L1, drives the differentiation of CD14+CD1a- immature myeloid cells, anergic T cells and Tregs, induces tolerance, and promotes tumor growth." (PMID 30200478, 2018). "TAM2 and MDSCs are well known for their ability to suppress T cell-mediated tumor killing since both can exert direct immunosuppressive effects using cell-cell contact (e.g., CD80 and PD-L1), secreted factors (e.g., IL-10 and TGF-β) and expression of enzymes (e.g., ARG-1, iNOS, IDO)." (PMID 30233579, 2018). "Tumor cells were largely negative for Arg1 staining with the exception of HCC." (PMID 29254508, 2017). "Indeed, in murine studies, injection of the arginase inhibitor nor-NOHA or genetic disruption of Arg1 in the myeloid compartment resulted in reduced tumor growth, indicating that Arg1 is pro-tumorigenic." (PMID 29254508, 2017). "The ARG-1 mRNA level in tumor blocks, the frequency of Tregs, and IL-10 level were not affected." (PMID 27246354, 2016). "Interestingly, depletion of MPs in tumors did not prevent MG polarization, suggesting direct influence of tumor-specific factors on MG Arg1 upregulation." (PMID 27936099, 2016). "Dying tumor cells release various factors (e.g., TGF-β, interleukin-10, or sphingosine-1-phosphate) that lead to M2 polarization of macrophages, which express high levels of arginase-1, ultimately resulting in reduced intratumoral NO abundance, thus contributing to tumor progression." (PMID 27034586, 2016). "Here, MG were located at the tumor edge and did not express high levels of Arg1." (PMID 27936099, 2016). "Although the expression of the M2 marker Arg-1 was not modified in GAMs, the enhanced expression of iNOS indicates that peptide R interferes with the phenotype switching of GAMs towards M2 pro-tumorigenic functions induced by the cross-talk with tumor cells." (PMID 27015814, 2016). "Although it was not examined here, tumor debulking may also abate tumor immunosuppressive signals and reverse the expression of Arg1 by MG surrounding the tumors." (PMID 27936099, 2016).
tumor (continued). "Expression of Arginase-1 (Arg-1), Found in inflammatory zone-1 (Fizz-1), chitinase 3-like-3 (Ym- 1), mannose receptor (MRC1/CD206) and Macrophage galactose-type C-type lectins 2 (MGL-2) were increased in B16F10-ARF−/− tumor xenografts, confirming M2 polarization of macrophages." (PMID 27572316, 2016). "Moreover, recent data from syngeneic murine tumour models of Lewis lung carcinoma (LLC) and B16-F1 (B16) melanoma cancer cell lines showed that lactate-induced stabilisation of HIF-1α increased arginase 1 expression and consequently M2-like polarisation of tumour-associated macrophages." (PMID 26099350, 2016). "Thus, it has recently been proposed for certain syngeneic transplantable solid murine tumors that lactate production by the tumor cells generates a conserved, “alternative activation-like” TAM signature that is orchestrated by HIF-1α and characterized by arginase-1 and VEGF activation." (PMID 25702581, 2015). "Furthermore, our data were in line with the suggestion that MDSCs from tumor-bearing hosts, as characterized by a high level of iNOS/NOS2 and Arg-1, are potent inhibitors of Ag-specific T cell functions that are able to suppress T cells in an Ag-independent manner." (PMID 26497849, 2015). "However, levels of ARG1 and iNOS were significantly increased by Tg treatment in tumor-infiltrating MDSCs, but not in splenic MDSCs." (PMID 25514597, 2014). "Moreover, inhibition of ARG1 and iNOS activity in MDSCs can be achieved by phosphodiesterase-5 (PDE5) inhibitors (sildenafil, tadalafil, and vardenafil), which can restore the spontaneous anti-tumor T cell response." (PMID 24605112, 2014). "In murine tumor models blockage of MCP-1 does not affect overall tumor associated macrophage number, but results in a skew of macrophage phenotype with reduced expression of M2 markers (CD206 and arginase 1) and slight up-regulation of the M1 marker inducible nitric oxide synthase (iNOS)." (PMID 24432024, 2014). "Collectively, these data are consistent with the hypothesis that arginase-1 producing TAMs present in the tumor microenvironment induce local, but not systemic, suppression of anti-tumor immunity following injection of MCA-205-OVA tumor cells." (PMID 24614600, 2014). "Within the tumor microenvironment, in the absence of Rip2, we found a cytokine signature enriched in IL-4 and G-CSF, polarizing towards a M2 phenotype as reflected in increased production of IL-10 and arginase-1." (PMID 24733360, 2014). "Importantly, arginase-1 is usually only suppressive in the tumor microenvironment locally and does not lead to systemic immunosuppression." (PMID 24614600, 2014). "Interestingly, only invasive EMPD possessed substantial numbers of CD163+ M2 macrophages and MMP-9+ cells, B7H1+ cells, and ARG1+ cells around the tumor, whereas few CD163+ M2 macrophages, MMP-9+ cells, B7H1+ cells, and ARG1+ cells were observed in noninvasive EMPD." (PMID 23606867, 2013). "Moreover, it has been shown that FOXO 1 can not only target tumor cells, but also inhibit the progression of HCC by inducing and recruiting macrophages to antitumor differentiation, while inhibiting the expression of CD206, IL‐10, Arg‐1(Arginase 1, Arg‐1), and IL‐6 mRNA in macrophages." (PMID 41002121, 2025). "After TFF3 depletion, the expression of M2 markers (CD163, CD206, ARG-1, and IL-10) and S100A4 and S100A8 were remarkably downregulated, which confirmed our hypotheses that iCCA cells induce the M2 phenotype and pro-tumor polarization of resident macrophages by secreting TFF proteins." (PMID 39256888, 2024).
tumor (continued). "Notably, Arg1 expression in TAMs and tumors can be inhibited with PI3Kγ inhibitors, and PI3Kγ deletion promotes the development of NOS, which may accelerate the creation of tumor-killing NO from L-arginine." (PMID 38185636, 2024). "Considering the findings for M-MDSC, ARG1, soluble VISTA, Treg cells, IL-10, and soluble TIMD-4, it can be suggested that immunosuppression at the periphery has a significant impact, sustaining impaired systemic immunity, which may limit the anti-tumoral immune response at the tumor site." (PMID 39502689, 2024). "Given prior observations of ARG-1 production by TANs and ARG-1 blockade reducing tumour growth in an animal model of NSCLC, the authors suggested that tumours with highly frequent granulocytes in either tumour or stroma could be targeted with ARG-1-blocking therapy." (PMID 37835491, 2023). "Therefore, to explore the use of ARG1 as a pro-metastatic marker and go beyond its immunosuppressive role, we characterised the Arg1 gene and ARG1 protein expression, as well as its cellular source and activity in metastatic and non-metastatic tumours." (PMID 37980483, 2023). "Thus, targeting the metabolic aberrations in tumor morphogens (CAFs) to reprogram the metabolism in macrophages and modulating the expressions of ARG1, MRC1, and MAPK signaling might lead to the discovery of novel therapeutic strategies." (PMID 33198082, 2020). "Moreover, ARG1-derived products, i.e. polyamines, could directly contribute to the generation of tolerogenic DCs through IDO1 phosphorylation, thus sustaining the immunosuppressive tumor microenvironment." (PMID 31533831, 2019). "We also identified that ARG1 functioned as an oncogene in HCC, based on the fact that knockdown of ARG1 by shARG1 interference could decrease cell proliferation activity and motility of HCC cell, while ARG1 overexpression could promote tumor-related phenotypes in HCC cells." (PMID 30320132, 2018). "In addition, the interaction of Paget cells with other cells, such as LECs and CD163+Arg1+ macrophages in a tumor through the CXCR4–SDF-1 signaling and RANKL–RANK signaling, respectively, could establish a favorable tumor microenvironment to promote metastasis of Paget cells." (PMID 29503810, 2018). "The decrease in CD4 and Arg-1 in Cysltr1−/− mice could be explained by the finding that CD4+ Th2 cells can facilitate the expression of arginase-1 in murine macrophages, and arginase itself can promote tumor growth and the down-regulation of tumor cytotoxicity." (PMID 28410235, 2017). "Treatment of either CD33+ or CD11b+ tumor-cell line-induced MDSC with lipopolysaccharide, a known activator of MDSC function, caused further up-regulation of STAT3, C/EBPβ, and HIF1α concurrent with increased expression of ARG-1, iNOS, and NOX2-component NCF1 (data not shown)." (PMID 21658270, 2011). "Despite M2 macrophages’ similar tumor-promoting role, Rnaseh2c-cKO did not affect M1 (CD80, CD86) or M2 (CD163, ARG1) marker expression in mouse HCC-infiltrating macrophages." (PMID 41361104, 2025). "Unlike Arg1 and STAT3 inhibitors, which generally aim to suppress specific immune-suppressive pathways, IL-19 antibody therapy directly modulates the tumor microenvironment by addressing aberrant cytokine signaling." (PMID 40057744, 2025). "Many infiltrating macrophages are positive for M2-macrophage marker arginase (ARG1) but negative for M1-macrophage marker nitric oxide synthase 2 (NOS2), indicative of a tumor-supportive microenvironment." (PMID 38422022, 2024). "Blockade of M-MDSC-derived IL-10, but not Arg1 or iNOS, released human CRC tumour M-MDSC-mediated suppression on T cells and restored T cell proliferation." (PMID 38464388, 2024). "The TAMs and lymphocytes had strong communication with the tumour cells in the responders, while in the non-responders, the cytotoxic CD8+ T-cells were in close proximity with immunosuppressive arginase 1 and CCR6 expressing CD163− TAMs." (PMID 38386105, 2024).
tumor (continued). "Although TCM from B16 cells failed to induce ARG1/Arg1 expression in myeloid cells, an FIH-defective host environment can still create a tumor promoting TME, for example, via interactions between B16 cells and various FIH-defective cells, including T cells." (PMID 38422022, 2024). "While ARG1 was not expressed at a detectable level in BMDMs and in other brain tissue cells, the expression of ARG2 was present both in macrophages and tumor cells (data not shown)." (PMID 36054818, 2022). "In line with diminished IL-4 signaling, IL-4ra-KO mice exhibited low expression levels of the alternative macrophage marker genes Arg1 and Il-10, which furthermore, were not enhanced in iWAT in the presence of the cachexigenic LLC tumor." (PMID 35210363, 2022). "Strikingly, YFP+ (i.e. Arg1+) macrophages successfully recused tumor growth in Il9r−/− mice, while YFP- macrophages did not promote tumor growth." (PMID 35778404, 2022). "Anti‐Chi3L1 antibody‐treated tumor tissues promoted ARG1 and CD206 expression inhibition compared with vehicle‐treated tumor tissues but did not change iNOS and CD86 expression." (PMID 34861103, 2022). "Second, the mechanisms by which Arg-1 and GPC-3 promote tumor growth, metastasis, and recurrence in ICC patients were not evaluated in this study." (PMID 34715880, 2021). "Two ARG1 inhibitors, NOHA and nor-NOHA, have been tested in various cancer models and can diminish the immuno-inhibitory function of MDSCs and improve anti-tumor T cell response." (PMID 34988072, 2021). "Metabolic reprogramming in CRC includes overexpression of DDAHs and PRMTs in addition to ARG1 and NOS2 and is not restricted to tumor tissue but can be modulated by novel oxicam analogues." (PMID 32932854, 2020). "In tumor tissues of PDAC patients, nMDSCs, but not mMDSCs, were found to be significantly increased and arginase 1 (ARG1) was predominantly expressed by nMDSCs." (PMID 33117704, 2020). "Immunohistochemical staining showed that the tumor cells were negative for AE1/AE3, CK18, CK7, CK19, Hepatocyte Paraffin-1, Glypican-3, Arginase-1, CD56, Chromogranin A, Synaptophysin, Vimentin, and Carcinoembryonic antigen." (PMID 31488173, 2019). "We further found an increase in regulatory cytokines including Il10 and Arg1, but not pro-inflammatory cytokines such as Il6, Tnfa and Il12 in DIO tumours compared with normal tumours using purified CD11b+ myeloid cells." (PMID 27708283, 2016). "In addition, there was no significant impairment of Ki67+ tumor cell proliferation nor changes in the tumor infiltration of CD4+, CD8+, FoxP3+ nor Arg1+ cells." (PMID 41226782, 2025). "Using the arginase-1 inhibitor Nω-hydroxy-nor-arginine (nor-NOHA) alone or in combination with the PD-1 inhibitor nivolumab, a significant reduction in arginase-1 activity and tumor mass was recorded." (PMID 40868818, 2025). "Tumour and peripheral blood MDSCs isolated from human CRC cancer patients potently inhibited T cell proliferation ex vivo, and pharmacological inhibition of IL-10 but not Arg1 of iNOS reversed the immunosuppressive effect of MDSCs in a human CRC study." (PMID 38464388, 2024). "The C8 cluster prevalent on the tumor periphery of rIL7-treated tumors exhibited the highest T cell, macrophage, and DC signatures and expressed higher levels of MHC class II (H2-Aa and H2-Eb1) and Pf4 genes rather than Arg1 genes." (PMID 38424167, 2024). "However, adropin in tumor stroma cells was positively correlated with local CD68 and ARG1 without any effects on iNOS." (PMID 37904094, 2023). "In the TME, owing to a lack of Arg1 and NOS in T lymphocytes, arginine may be consumed by Arg1 and NOS in tumor cells or myeloid cells leading to excessive arginine consumption and a weakening of the Teff immune response." (PMID 37277776, 2023). "In our tumor models, both TLR2 and TRL4 were expressed on ARG1+ TANs but absent on ARG1– TANs." (PMID 36377658, 2022).